STAT1 (signal transducer and activator of transcription 1)
Diseases named in the same sentence as STAT1 in open-access papers (continued):
Sharing a sentence is not in itself a finding about the gene and the disease.
infection (continued). "In vivo, greater enterocyte infection by WNV was observed after subcutaneous virus inoculation in animals with deficiencies in STAT1 or type I IFN signaling function." (PMID 37749080, 2023). "Increased viral susceptibility was found in mice with deficiencies in MyD88, CCR6, and Stat1 while B6 mice only showed transient infection." (PMID 38133335, 2023). "STAT1 activates the transcription of genes with crucial antiviral properties, and the selective gene deletion of STAT1 in mice or the presence of loss-of-function mutations of STAT1 in humans both cause rapid death from severe infections." (PMID 35456913, 2022). "We find that despite robust activation and recruitment of immune cells from the blood to the brain during infection, STAT1 deficiency in microglia leads to increased brain parasite burden and uniform lethality in mice when challenged with T. gondii." (PMID 36067217, 2022). "LASV-infected Stat1-KO mice started showing weight loss at 4 days post-infection (d.p.i.)and symptoms, such as scruffy coat, hunched back, and lethargy started at 6 d.p.i. simultaneously with hypothermia." (PMID 35605008, 2022). "In this study, we defined the effect of T cell-specific STAT1 deficiency on the viral and host parameters of infection with murine gammaherpesvirus 68 (MHV68)." (PMID 35968944, 2022). "Though poly(I·C) augmented STAT1 phosphorylation in B.6 infection, its extent was masked by the higher basal level of phosphorylation caused by the infection." (PMID 36073824, 2022). "STAT1 gene deletion in mice and complete STAT1 deficiency in humans both cause rapid death from severe infections." (PMID 35456913, 2022). "Similar experiments using CE(NiP) virus mutated to prevent P protein-STAT1 interaction indicated that infection at MOI of 0.001 followed by IFN treatment at 1 day post-infection (dpi) resulted in substantially decreased titers of the mutant virus." (PMID 35576230, 2022). "The authors quantified hearing loss by measuring the magnitude of movement in response to sound and found that hearing loss in the STAT1 KO mice appeared to be progressive starting from day 29 post infection." (PMID 35758052, 2022). "Accordingly, studies in mice and humans reveal that subjects with mutations in STAT1 are susceptible to infection by viral and bacterial pathogens, highlighting the essential role of STAT1 during infection." (PMID 34497340, 2022). "Consistent with previous results, the upregulation of STAT1 expression over time shows that HAstV1 infection in organoids is linked to an IFN‐mediated response." (PMID 34309190, 2021). "We describe a case of CMC with disseminated Talaromyces marneffei infection caused by a new pathogenic Y287N mutation at amino acid 287 in the coiled-coiled domain of STAT1, which was identified using whole-exome sequencing." (PMID 34421897, 2021). "To test the susceptibility of STAT1-/- mice to infection, we infected them with avirulent HSV-1 strain KOS (2 X 105 pfu/eye) without corneal scarification and used WT 129SVE parental mice as controls." (PMID 34653236, 2021). "In line with previous papers, AR complete STAT1 LOF patients were likely to cause life-threatening infections by mycobacteria and viruses." (PMID 33777053, 2021). "Patients with AR partial STAT1 LOF mutations were susceptible to infection by intracellular bacteria (Salmonella or mycobacteria) and viruses." (PMID 33777053, 2021). "Patients with partial or complete loss of STAT1 functions are susceptible to infection suggesting that the actions of STAT1 are indeed essential in the inflammatory responses of IFN to pathogen infection." (PMID 32991625, 2020). "We note, however, that during a study examining the effect of Rux on NK cell function in patients with STAT1 gain-of-function mutations, a single patient with chronic norovirus infection appeared to clear the infection following Rux treatment." (PMID 32184238, 2020).
infection (continued). "We found that HMPV infection of STAT2-deficient U6A cells led to reduction of STAT1 and pSTAT1 in a dose-dependent manner with increasing MOI." (PMID 32635475, 2020). "The importance of STAT1 to the immune response is evident from our previous finding that mice deficient in STAT1 develop a lethal, host immunity-mediated disease following infection with the otherwise harmless lymphocytic choriomeningitis virus (LCMV)." (PMID 32310998, 2020). "It was shown previously that super-infection with pathogenic S. aureus leads to the enhancement of viral titers due to the inhibition of STAT1 and STAT2 dimerization, resulting in decreased production of anti-viral factors." (PMID 33333815, 2020). "The results showed that Stat1/2−/− adult mice also were highly susceptible to NoV and 60% of the Stat1/2−/− mice succumbed within 30 days of infection with NoV, which was accompanied with significant weight loss." (PMID 32753500, 2020). "STAT1 has been identified as a critical mediator of the innate leukocyte response to infection, and the loss of STAT1 is correlated with compromised bactericidal ability." (PMID 31555304, 2019). "Consistent with the peak of viral titers in these mice, we observed that gastrointestinal MNV infection caused diarrhea only in Stat1-/- mice at three days post-infection." (PMID 31017981, 2019). "Upon infection in vivo, neuron-specific STAT1-deficiency (Stat1N−/−) leads to high viral titers in the TG and brain stem and the development of HSE." (PMID 30167845, 2018). "More research is required to investigate the mechanisms associated with IFN-γ and IL-17 cytokine production, distinct types of STAT1 mutations, and the resulting susceptibility to different infections." (PMID 29270166, 2017). "We observed that CSFV infection induced the expression of type III IFNs, enhanced the phosphorylation of STAT1, and caused up-regulation of several critical ISGs in PK-15 cells and pigs after the infection." (PMID 29312239, 2017). "This kind of Stat1 mutations lead to reduction in overall Stat1 expression and signaling responses and are ultimately fatal due to overwhelming infections and inflammation." (PMID 28184222, 2017). "Since Lm is known to potently induce IFN expression, we chose human STAT1-deficient fibroblasts as the primary host cell type for infection." (PMID 28002492, 2016). "Hep3B cells have a low susceptibility to Sinbis virus infection, however, where STAT1 is knocked-down infection is significantly increased." (PMID 27367734, 2016). "In contrast, heterologous simian RV (RRV strain) was found to replicate poorly in WT mice, but RRV infection of STAT1-deficient suckling mice resulted in substantially enhanced intestinal replication and efficient systemic virus replication and disease." (PMID 27128797, 2016). "Infection studies in Stat1 deficient mice for instance showed an increased Leishmania intracellular growth that was associated with an increase in phagosomal pH." (PMID 28036391, 2016). "IFN-γ signaling is critical in controlling parasite replication during this phase, and mice deficient in IFN-γ or STAT1 rapidly succumb to infection." (PMID 26196739, 2015). "Part of this evidence is supported by the fact that the viral load in STAT2 deficient mice was lower than their STAT1 counterparts at multiple time points after infection." (PMID 25768016, 2015). "In the present study, we revealed the crucial role of STAT1 in reducing the susceptibility to T. cruzi infection and, in addition, identified the infection-regulated ido gene responsible for parasite killing to be under the transcriptional control of STAT1." (PMID 25340519, 2014). "Both LR-82R and LR-79K infections were lethal to the STAT1-deficient mice, however, supporting our prior contention that MSD and fatality are not closely linked." (PMID 24587470, 2014).
infection (continued). "For example, MNV-1 causes a lethal infection with symptoms such as encephalitis, hepatitis, and pneumonia in STAT1 knockout mice, whereas MNV-O7 causes a subclinical infection in these mice." (PMID 24847970, 2014). "In the present study, we report that the transcription factor STAT1 (signal transducer and activator of transcription 1) reduces the susceptibility of human cells to infection with T. cruzi." (PMID 25340519, 2014). "This regulation seemed to be directly linked to deficiency of Timp3, as infection of these cells with TIMP3 adenovirus promptly decreased STAT1 mRNA and protein expression to control levels." (PMID 23401241, 2013). "To overcome the limitations posed by the exquisite sensitivity of Stat1−/− mice to infections with Lm or other pathogens we generated mice with floxed Stat1 alleles." (PMID 22719255, 2012). "Infection with DENV decreases type I IFN-mediated STAT1 phosphorylation and also causes a proteasome-dependent decrease in STAT2 protein levels." (PMID 22590678, 2012). "The critical importance of Stat1 for resistance to infection is emphasized by mutations of the Stat1 gene in humans." (PMID 22719255, 2012). "Whereas this was not confirmed in human fibroblasts, Kim and colleagues instead implicated a dephosphorylation of nuclear STAT1 in particular following infection with type I strain parasites." (PMID 22275866, 2012). "Infection of immunized mice with Lm caused a drastic change in the consequences of Stat1 signaling in cell types of the immune system." (PMID 22719255, 2012). "The importance of clearing Lm in the liver is underscored by our findings that the death of mice with different Stat1 genotypes correlated well with the inflammatory infiltrate in this organ and with the hepatotoxicity caused by infection." (PMID 22719255, 2012). "An intact IFNγ pathway is essential to combat infection initiated from a wide range of microbial pathogens; therefore patients with genetic defects in Stat-1 signaling are susceptible to microbial infections." (PMID 22253910, 2012). "At 12, 18, and 24 hours post-infection, the high viremia observed in the single- and double-deficient strains (all p<0.0005) demonstrates that the combined function of both STAT1 and STAT2 is required for effective control of viral replication." (PMID 21379341, 2011). "This virus, which represents the closest available progenitor of the original isolate of MNV identified in 2003, causes a lethal infection in STAT1-/- mice." (PMID 22174679, 2011). "In contrast to the single-deficient mice, viremia in STAT1−/−/2−/− mice increased 25-fold between 24 and 72 hours after infection." (PMID 21379341, 2011). "The ability of WT-v and M1-v viruses to infect and cause disease in the STAT1-/- mouse model was then examined by oral infection of age and sex matched mice." (PMID 22174679, 2011). "By utilizing in vitro Leishmania infection assays we identified a selective defect in phagosomal acidification in Stat1-deficient macrophages, which resulted in a twofold increase of intracellular parasite survival during a 5 days infection period." (PMID 19381261, 2009). "Viral titers in tissues of infected mice have not been reported to exceed 106 PFU/ml, and this highest level of viral titer is obtained after infection of highly susceptible STAT1-/- mice." (PMID 19079577, 2008). "Importantly, infection with LSDV122-deficient virus (LSDVΔ122) enhanced IFN-β-induced phosphorylation of STAT1 and STAT2, as well as transcription of downstream antiviral ISGs compared to wild-type LSDV." (PMID 41525414, 2026). "In addition, we found that the expression of p-STAT1 and STAT1 were enhanced in Sec10-deficient BMDMs and PMs than that in wild-type macrophages upon infection with VSV and HSV-1 or stimulation with poly(I:C) and poly(dA:dT)." (PMID 40920886, 2025).
infection (continued). "Previous studies have used type-I interferon receptor-knockout mice with either C57BL/6 or 129 backbone, STAT-1 knockout mice and mice treated with cyclophosphamide to establish infection models of human pathogenic orthonairoviruses such as CCHFV and Dugbe virus." (PMID 38502642, 2024). "Additionally, STAT1 has also been implicated in promoting infections related to virus and bacterial diseases." (PMID 39539545, 2024). "We found that T. gondii-infection-induced STAT1 phosphorylation declined faster in Fam96a-deficient BMDMs than that in the WT controls, suggesting Fam96a may be involved in regulating IFN signaling." (PMID 38713713, 2024). "Interestingly, we found that STAT1 deficiency resulted in increased susceptibility to infection compared to deficiency in IFNγ alone." (PMID 39440975, 2024). "Mutation and knockdown of STAT1 gene help in the study of the infection and disease pathogenesis." (PMID 39539545, 2024). "We hypothesized that deficiencies in either CCR2 or STAT1 proteins inhibit host defense against MmuPV1 infection, leading to increased viral replication and transcription in infected tongues." (PMID 38133335, 2023). "To identify the targets of WNV infection in the culture, we stained enteroid monolayers with Abs against WNV and different cell markers, and found that WNV infects villin- and EpCAM-expressing epithelial cells in STAT1-deficient monolayers, compared to limited infection in wild-type enteroids." (PMID 37749080, 2023). "Because the ependyma is both directly infected with MuPyV and can be inflamed indirectly via the activation of TLRs, loss of STAT1 specifically at this barrier leads to increased neuroinflammation after MuPyV infection (SA Spencer and AE Lukacher, unpublished observations)." (PMID 37896889, 2023). "Effect of T cell-intrinsic STAT1 deficiency on B cell populations during MHV68 infection." (PMID 35968944, 2022). "Effect of T cell-intrinsic STAT1 deficiency on T cell populations during MHV68 infection." (PMID 35968944, 2022). "T cell-specific STAT1 deficiency leads to decreased infection of B cells in the spleen." (PMID 35968944, 2022). "Typically, overlap of mycobacterial and viral phenotypes occurs where the defective signaling molecule is shared by both pathways, for example in TYK2 or STAT1 deficiency, although the degree of infection susceptibility depends on how and to what extent signaling is impaired." (PMID 36159783, 2022). "STAT-1-/- mice are also susceptible to infection caused by ML29 and MOPV." (PMID 33573250, 2021). "A number of other immunocompromised or chimeric strains of mice such as NOD-SCID, SCID-PBL, NOD/SCID/IL-2R-/-, and STAT1-/- mice are susceptible to infection depending on virus serotype, and these do show signs of infection seen in humans including rash, fever, and thrombocytopenia." (PMID 33804381, 2021). "Interestingly, patients with mutations in STAT1 gene are susceptible to infections including ear infections." (PMID 32991625, 2020). "Given the distinct target cell types, tissue tropism, and pathogenesis between MNoV strains, we next tested whether Cd300lf-/-Stat1-/- mice were susceptible to MNoVCR6 infection." (PMID 32251490, 2020). "It has been reported that LASV LF2384 causes lethal infection in Stat1 knockout mice." (PMID 31554720, 2019). "Because immunodeficient mice are more susceptible to DENV infection, we further established a lethal infection mouse model in STAT1-deficient mice (STAT1−/− mice) to test the prophylactic and therapeutic effects of these modified NS1-WD-peptide specific Abs against lethal DENV 2 infection." (PMID 28765561, 2017). "Infection with T. gondii interferes with host cell signaling pathways implicated in protective immunity, for instance by blocking the transcription factors signal transducer and activator of transcription 1 (STAT1) and nuclear factor kappa-light-chain-enhancer of activated B cells (NF-κB)." (PMID 27003162, 2016).
infection (continued). "Importantly, the GFP fluorescence intensity of infected STAT1-deficient fibroblasts increased over the course of infection due to bacterial replication and accumulation in initially invaded cells." (PMID 28002492, 2016). "Interestingly, the severity of infection was suggested to be dependent in this model at least partially to loss of STAT-1-dependent regulation of T cell homeostasis which resulted in T cell infiltration and damage to the cochlear nerve." (PMID 27191716, 2016). "It has previously been reported that MNV-1 causes lethal infection in Stat1-/- mice." (PMID 27294868, 2016). "Moreover, infection of TLX deficient mice with the intracellular parasite Toxoplasma results in impaired production of the STAT1-dependent cytokine interleukin-12 by dendritic cells and increased parasite burden in the brain during chronic infection." (PMID 26196739, 2015). "Based on this model, our observed pattern of viral titers in the TG predicts that WT virus would cause significantly more periocular infection and disease than Δγ34.5 in Stat1fl/fl mice, and this should be normalized in Stat1N-/- mice, despite the presence of STAT1-dependent responses in the skin." (PMID 26153886, 2015). "STAT-1 knockout mice have also been shown to be highly susceptible to infection by LASV." (PMID 26266264, 2015). "Collectively, these changes in gene expression programs following infection by NBL describe a robust early induction of STAT1-dependent genes and subsequent loss of myofibers, a strong regenerative response, and a shift in the sources of energy in infected muscle." (PMID 26720604, 2015). "However, LR-79K infection of the STAT1-deficient mice caused only mild MSD compared to CHIKV-LR and LR-82R, from which we infer that LR-79K is substantially more attenuated for ability to cause MSD than LR-82R or even the 181/25 LAV." (PMID 24587470, 2014). "However, STAT1 deficient mice show increased susceptibility, prolonged virus shedding and mortality following infection with either virus." (PMID 20386712, 2010). "The increased replication of HSV-1 in STAT1-/- DCs and macrophages shown here might be an important factor contributing to increased susceptibility of STAT1-/- mice to infection." (PMID 19439086, 2009). "Investigation of the role of type I interferon (IFN-α/β) in protection of mice from viscerotropic YFV infection revealed that mice deficient in the IFN-α/β receptor (A129) or the STAT1 signaling molecule (STAT129) were highly susceptible to infection and disease, succumbing within 6–7 days." (PMID 19816561, 2009). "In addition, our findings demonstrate that purified IgG from anti-IFN-γ IgG-positive SLE patients could neutralize IFN-γ, and further impair IFN-γ-induced STAT1 phosphorylation, which is related to the susceptibility and severity of infection in SLE." (PMID 37857784, 2024). "However, increased reactivation could result from increased MHV68 infection of B cells that differentiate via an extrafollicular route, including IgD+ plasmablasts that are increased in mice with T cell-specific STAT1 deficiency." (PMID 35968944, 2022). "In addition, this recessive STAT1 deficiency is characterized by altered IL-27 and IFNλ signaling pathways, which are conditions that may contribute to susceptibility to infections." (PMID 35456913, 2022). "However, further research has shown that STAT1 GOF variants may increase susceptibility to infection by other intracellular pathogens." (PMID 36102410, 2022). "Interestingly, IC infection of STAT1-deficient mice results in the same wasting disease rather than classical LCM, suggesting that development of classical LCM relies on multiple factors including controlled virus replication and spread, and a precisely tuned antiviral host response." (PMID 30791575, 2019). "Thus, flow cytometry is a well-suited method to measure Lm infection of STAT1-deficient fibroblasts as it is capable of detecting specific infection defects that may arise due to ISG expression." (PMID 28002492, 2016).